SOX2 (SRY-box transcription factor 2)
Diseases named in the same sentence as SOX2 in open-access papers (continued):
Sharing a sentence is not in itself a finding about the gene and the disease.
prostate carcinoma (continued). "In prostate cancer, in vitro and in vivo xenograft experiments using DU145 SOX2-overexpressing cells in NOD/SCID mice revealed that SOX2 caused an increase in apoptotic resistance by decreasing store-operated Ca2+ entry via repressing ORAI1 expression." (PMID 25114775, 2014). "Previous studies have also suggested that certain cancers, including prostate cancer, express Sox2 and OCT4 simultaneously, and their expression has been associated with the differentiation of tumors." (PMID 25120646, 2014). "Over-expression of Sox2 in human breast cell line-MDA231 and human prostate cancer cell line DU145 causes enhanced migration capacity and decreased levels of E-cadherin, DKK3 and increased a-SMA, DVL1 and DVL3." (PMID 24618337, 2014). "Expression of Sox2 is also increased within prostate cancer cells that are resistant to the anti-androgen MDV3100." (PMID 23326489, 2013). "In normal prostate epithelial cells, human embryonic stem cells, and castration-resistant prostate cancer cells, ligand activation of AR promotes a decrease in Sox2 expression, which is a result of direct binding of the AR to the Sox2 cis-enhancer region." (PMID 23326489, 2013). "Time course analyses of Sox2 mRNA expression documents that within 30 minutes there is a statistically-significant (p<0.05) decrease in Sox2 mRNA expression within CWR-R1 prostate cancer cells." (PMID 23326489, 2013). "In castration-sensitive prostate cancer cells, Sox2 expression is sufficient to promote castration-resistant tumor formation." (PMID 23326489, 2013). "To test this, we ectopically expressed Sox2 in the castration-sensitive LAPC-4 prostate cancer cell line." (PMID 23326489, 2013). "The detection and AR regulation of Sox2 in castration-resistant CWR-R1 cells suggested that Sox2 expression increases in response to host castration or AR inhibition and thus promotes castration-resistant prostate cancer cell growth." (PMID 23326489, 2013). "From results of immunohistochemical staining, we found either cytosol or both nuclei and cytosol localization of SOX2 in cancer cells, which was consistent with our previous findings in human prostate cancer cells." (PMID 22615765, 2012). "Additionally, c-Fos upregulates downstream effectors, including FOXC1 and SOX2, driving neuroendocrine differentiation in prostate cancer." (PMID 42225654, 2026). "Therefore, down-regulating SOX2 expression in prostate cancer cell lines can markedly improve their sensitivity to androgen receptor signaling inhibitors." (PMID 39976818, 2025). "SOX2 has been demonstrated to enhance the resistance of prostate cancer cells to paclitaxel through the PI3K/Akt signaling pathway, promote cellular proliferation, and display anti-apoptotic characteristics, thereby facilitating the emergence of hormone-refractory prostate cancer." (PMID 39976818, 2025). "Moreover, SOX2 is capable of disrupting the cell cycle, which results in resistance to nuclear hormone receptor inhibitors in prostate cancer." (PMID 39976818, 2025). "SOX2 is considered to enhance the proliferation and survival of prostate cancer cells." (PMID 39976818, 2025). "SOX2 has the ability to facilitate the transformation of prostate cancer lineages." (PMID 39976818, 2025). "Below are several ways in which SOX2 plays a role in the advancement of prostate cancer." (PMID 39976818, 2025). "We and others have identified other members of the pluripotent stem cell transcriptional circuitry as being important AR-regulated oncogenes in prostate cancer, including SOX2 and NANOG; however, we rarely see these co-expressed in cancer, or in particular, expressed with OCT4." (PMID 39858088, 2025). "SOX2 correlates with prostate cancer progression, invasion and metastasis." (PMID 39976818, 2025).
prostate carcinoma (continued). "Research has demonstrated that the levels of SOX2 expression in prostate cancer tissues are markedly higher than those found in normal prostate tissues, and this elevated expression correlates with the prognosis of prostate cancer." (PMID 39976818, 2025). "This may provide an explanation to the discrepancies seen with NKX3.1’s role in early-stages of prostate cancer, given that factors like SOX2 are AR-repressed and upregulated after androgen targeted therapy and promote therapeutic resistance." (PMID 39858088, 2025). "Furthermore, it has been shown that SOX2 contributes to castration resistance and lineage plasticity in prostate cancer." (PMID 39976818, 2025). "SOX2: Elevated expression in 76% of colorectal, 60% of breast, and 72% of prostate cancers." (PMID 40674376, 2025). "There is increasing evidence suggesting that SOX2 is crucial for the initiation, progression, invasion, metastasis, and treatment resistance of prostate cancer, therefore understanding the mechanism of SOX2 in prostate cancer can provide better targets for the treatment of prostate cancer." (PMID 39976818, 2025). "SOX2 mRNA and protein are found in most prostate cancer cells." (PMID 39976818, 2025). "Given that higher Gleason grades correlate with worse prognosis, it is suggested that SOX2 may play a role in the development of prostate cancer and could be significant in its clinical progression." (PMID 39976818, 2025). "Additionally, we can employ small interfering RNA (siRNA) or short hairpin RNA (shRNA) techniques to specifically silence the SOX2 gene, leading to a decrease in its expression and subsequently inhibiting the growth of prostate cancer." (PMID 39976818, 2025). "The study revealed that ASCL1, a transcription factor oriented towards neuronal lineage, serves as a key driver for the transcription of plastic neurons within this lineage and directly modulates SOX2, promoting the differentiation of prostate cancer into NEPC." (PMID 39976818, 2025). "This metabolic reprogramming mechanism induced by SOX2 could modulate sorts of malignant tumor cells to enhance aggressive phenotypes, drug resistance and metastatic ability, such as in melanoma and prostate cancer." (PMID 39133273, 2024). "In prostate cancer, SOX2 overexpression has emerged as a critical marker for evaluating metastasis." (PMID 38494478, 2024). "SOX2 ChIP-seq data was derived from the wildtype of the prostate cancer cell lines CWR-R1 and WA01." (PMID 36932385, 2023). "SOX2 was overexpressed in several tumor types, including lung and prostate cancer." (PMID 35473511, 2022). "Sox2/Oct4 positive cells that isolated from prostate cancer tissues have the stem cell properties." (PMID 35342431, 2022). "Indeed, prostate cancer MICs can upregulate SOX2 protein via TGF‐α-mediated activation of the EGFR/PI3K/AKT pathway." (PMID 36118530, 2022). "Nanog, Sox-2, and Oct-4 promote tumor formation in ovarian cancer and prostate cancer." (PMID 36605595, 2022). "Results showed that eNOS overexpression could induce remarkable upregulation of multiple CSCs markers (CD133) and stemness-associated genes, especially transcription factors NANOG and SOX2, in prostate cancer cells under adherent 2D culture." (PMID 35526071, 2022). "For example, in the case of prostate cancer, SOX2 levels rise in concert with increases in Gleason score, whereas in other cancers, such as SHH medulloblastoma, it is unclear whether SOX2 levels rise during tumor progression." (PMID 35454854, 2022). "CD44, CD133 and SOX2 are considered to be the major cancer stem cell markers in prostate cancer." (PMID 35365766, 2022).
prostate carcinoma (continued). "Similarly, CD117+/ABCG2+ cells isolated from 22Rv1 prostate cancer cells overexpress the core stem cell transcription factors, Nanog, Oct3/4, and Sox2, and the CSC marker CD133." (PMID 35800367, 2022). "Considering the critical roles of Sox2 in stem cells and prostate cancer development, we think Sox2 may contribute to establishing the stem cell colony at the first step." (PMID 35841025, 2022). "Finally, we show that inhibition of either TRIB2 or its downstream targets, BRN2 or SOX2, resensitizes resistant prostate cancer cells to enzalutamide." (PMID 34973338, 2022). "SOX2 promotes antiandrogen resistance through lineage plasticity in prostate cancer." (PMID 34809669, 2021). "Dysregulation of SOX2 expression contributes to progression of cancers, including prostate cancer." (PMID 34809669, 2021). "In prostate cancers, SOX2 could promote resistance to antiandrogen therapy (e.g. enzalutamide) by turning on lineage plasticity." (PMID 30517668, 2020). "Studies have indicated that H19 might act as an oncogene in prostate cancer by the upregulation of SRY box 2 (SOX2) and POU domain class 5 transcription factor 1 (POU5F1)." (PMID 32878251, 2020). "AR had been demonstrated to reduce cancer stemness by repression of CD44 and SOX2, on the contrary, loss of AR expression could upregulate STAT3 expression and lead to promote development of cancer stemness in prostate cancer cells." (PMID 32365531, 2020). "Prostate cancer cells can escape ADT through a change in lineage identity driven by elevated SOX2." (PMID 32146726, 2020). "RAGE and SOX2 were up-regulated in prostate cancer lesions, mainly in advanced grades, suggesting an active role of both antigens in the development and progression of prostate cancer and expecting the possibility of their use as therapeutic targets." (PMID 30806068, 2019). "Since a higher Gleason grade indicates a worse prognosis, so it is suggested that SOX2 may contribute to the tumorigenesis of prostate cancer and may play an important role in the clinical progress of prostate cancer." (PMID 30806068, 2019). "A very recent paper even reported that CT treatment of prostate cancer stem cells could inhibit their proliferation and tumorigenesis by downregulating the expression of stemness genes including Nanog, SOX2, Oct4, and CXCR4." (PMID 30972427, 2019). "As SOX2 was assumed to be a significant marker to evaluate the progression of prostate cancer, the treatment with metabolites from Halobacteriumsalinarum IBRC M10715 could prevent the progression of human prostate cancer." (PMID 31089359, 2019). "The analysis of the SOX2 and OCT4 expression in PC3 cells showed that the SORE6+ cell population expressed more of these proteins than the SORE6− population did, indicating that the SORE6 reporter can identify prostate cancer cells overexpressing SOX2 and OCT4." (PMID 31500347, 2019). "Furthermore, the EGFR-induced enhancement of the self-renewal capacity in prostate cancer cells correlates with an upregulation of Sox2." (PMID 29401647, 2018). "Previous research demonstrated that Sox2 expression increased chemoresistance in prostate cancer, suggesting that down-regulation of Sox2 might be a promising strategy to assist cancer therapy." (PMID 29228716, 2017). "Additionally, stable overexpression of SOX2 in PC3 prostate cancer cells promoted evasion of apoptosis in cells treated with paclitaxel." (PMID 28388544, 2017). "Consequently, androgen deprivation therapy can induce YAP1 expression, which in turn regulates downstream factors such as SOX2 and Nanog to promote PCa stem/progenitor like cells and contribute to castration resistant prostate cancer growth." (PMID 29383141, 2017).
prostate carcinoma (continued). "In addition, 82% (27/33) of SOX2+ prostate cancer cases were EZH2+ type, and 100% (33/33) of cases were CD44+." (PMID 27447616, 2016). "SOX2 overexpression in recurrent prostate cancer tissues has been reported." (PMID 27225481, 2016). "Moreover, a recent study shows that Sox2 is a critical regulator in self-renewal and tumor progression of human prostate cancer." (PMID 24618337, 2014). "Pluripotency-associated transcription factors, including NANOG, Sox2 and OCT4, are known as regulators of cellular identity in ES cells and have recently been identified in the epithelial malignancies of a variety of tissues, including prostate cancer." (PMID 25120646, 2014). "Resistance to the anti-androgen MDV3100 results in a marked increase in Sox2 expression within three prostate cancer cell lines, and in the castration-sensitive LAPC-4 prostate cancer cell line ectopic expression of Sox2 was sufficient to promote castration-resistant tumor formation." (PMID 23326489, 2013). "The expression of Sox2 in the castration-resistant CWR prostate cancer cell lines and the increased expression of Sox2 in isogenic castration-resistant cells inferred that Sox2 may confer castration resistance to prostate cancer cells." (PMID 23326489, 2013). "To test whether Sox2 expression was necessary for prostate cancer cell survival or castration-resistant growth, we targeted Sox2 expression using shRNA expression against Sox2." (PMID 23326489, 2013). "In terms of cancer, it was recently demonstrated that prostate cancer stem cells are characterized by high E-cadherin expression, are highly invasive, and exhibit high expression of stem cell markers Oct-3/4 and Sox2 compared to cells with low E-cadherin expression." (PMID 23176396, 2012). "Explore combination strategies that target OCT4 and other key master regulators—such as SOX2, MYC, EZH2, and BRN2—alongside immunotherapies, to more effectively disrupt the stemness and immune-evasive phenotypes associated with lineage plasticity in prostate cancer." (PMID 40722714, 2025). "Furthermore, these molecular conversion events might also result in an increase in the expression levels of stem-like gene products like SOX2, Oct3/4 and Nanog in prostate cancer cells." (PMID 39976818, 2025). "However, SOX2-positive tumors exhibited significantly faster metastasis after biochemical recurrence than SOX2-negative tumors, and SOX2-positive patients had higher prostate cancer-specific mortality and overall mortality rates." (PMID 40821114, 2025). "Additionally, it has been established that SOX2 interacts with the promoter region of β-catenin, indicating its direct role in regulating this gene's transcription and contributing to the metastasis of prostate cancer." (PMID 39976818, 2025). "Moreover, SOX2 expression in prostate cancer cells could also be further induced via palmitate supplementation to the in vitro co-culture system or via HFD in an in vivo co-xenograft mouse model." (PMID 37371076, 2023). "Moreover, let-7 has been found to maintain the cancer stem-like cell (CSC) phenotypes of prostate cancer, let-7 expression is controlled by LIN28A and LIN28B, and loss of let-7 increases the expression of SOX2 and promotes the cell transformation and expansion of prostate CSCs." (PMID 37596700, 2023). "In addition, TAMs was reported to regulate murine breast cancer stem cells through a novel paracrine EGFR/Stat3/Sox-2 signalling pathway and promote prostate cancer stem cells self-renewal and prostate cancer metastasis via activating β-catenin/STAT3 signalling." (PMID 38041196, 2023).
prostate carcinoma (continued). "Consequently, Rb1 loss in prostate cancer lead to EZH2 and Sox2 increase and gene expression widespread changes that leads toward a stem cell-like state that would facilitate the onset of metastasis, neuroendocrine transdifferentiation, and the acquisition of ADT resistance." (PMID 29888169, 2018). "As a pluripotent transcription factor, SOX2 overexpression in eutopic and ectopic endometrial specimens of ovarian endometriosis was expected to result in increased proliferation and inhibit apoptosis by targeting apoptosis-related proteins as it does in neural stem cells and prostate cancer." (PMID 24884521, 2014). "Thus, inhibiting the function of Sox2 and/or its target genes may have the potential to aid in the treatment of prostate cancer, and prevent progression to a castration-resistant state." (PMID 23326489, 2013). "AZGP1P2 overexpression enhances the sensitivity of castration-resistant prostate cancer cells to docetaxel, reduces migration, increases apoptosis, and reduces prostate CSC markers, including KLF4 and SOX2, in castration-resistant prostate cancer cells." (PMID 41431719, 2026). "This study evaluated the expression levels of SOX2, PIWI proteins, and MALAT1 in plasma samples from colorectal, breast, and prostate cancer patients, as well as healthy controls." (PMID 40674376, 2025). "The study investigated the expression levels of SOX2, PIWI proteins, and MALAT1 in plasma samples from patients with colorectal, breast, and prostate cancers, as well as a control group of healthy individuals." (PMID 40674376, 2025). "Prostate cancer cells react to the signals emitted by the TME, mainly TGF-β2, BMP-7, GAS6 and Wnt-5a, which can be conveyed via SOX2 and other transcription factors related to pluripotent stem cells." (PMID 39976818, 2025). "OCT4, in coordination with SOX2 and NANOG, acts as a master regulator of stemness and is frequently upregulated in prostate cancer stem cells (PCSCs)." (PMID 40722714, 2025). "Our study found that palbociclib affects the cellular iron and GSH content through TRIB3/SOX2/SLC7A11 signaling axis, disrupting the cellular redox balance and promoting ferroptosis in prostate cancer cells." (PMID 39362848, 2024). "STIM1 and SOX2 were discovered to have anti-apoptotic effects in pancreatic cancer cell lines, HCC, and prostate cancer." (PMID 38532463, 2024). "Collectively, these findings suggest that palbociclib induces ferroptosis in prostate cancer cells by inhibiting the expression of TRIB3, thereby reducing SLC7A11 expression via SOX2." (PMID 39362848, 2024). "In prostate cancer, SOX2 dysregulates the cell cycle via upregulating WEE1 and CDK1, resulting in the insensitivity of prostate cancer to NHRSI." (PMID 38331879, 2024). "Prior prostate cancer studies have also shown miR-145-5p can inhibit cell growth via other targets, including WIP1, PLD5, and SOX2." (PMID 38673886, 2024). "MiR-183-5p downregulates MUC15, inducing SOX2 expression via the c-MET/PI3K/AKT axis, while miR-653-5p upregulates SOX30 in prostate cancer." (PMID 38331879, 2024). "In prostate cancer, PAK2 enhances tumor plasticity by regulating SRY (sex-determining region Y)-box 2 (SOX2) expression, contributing to castration-resistant progression." (PMID 39769207, 2024). "METRO-TOPO also downregulated Oct-4 (41%), Sox2 (56%), and Nanog (49%) in taxane-resistant mCRPC (DUTXR) prostate cancer cell line model." (PMID 37476073, 2023). "METRO-TOPO downregulated Oct-4 (64%), Sox2 (60%), and Nanog (39%) in mCRPC/NEPC (PC-3M) prostate cancer cell line model." (PMID 37476073, 2023). "We also identified greater protein expression levels of Nanog, Sox2, and Oct4 genes in mCRPC/NEPC and taxane-resistant mCRPC/NEPC prostate cancer subtypes." (PMID 37476073, 2023).